AK1 (adenylate kinase 1)
Diseases named in the same sentence as AK1 in open-access papers (continued):
Sharing a sentence is not in itself a finding about the gene and the disease.
tumor (9 papers, 2019 to 2026). "Because in vitro analysis of AK1 showed increased Akt and NF-κB activities, we examined in vivo Akt and NF-κB activities of the tumor caused by AK1 injection into nude mouse." (PMID 31015491, 2019). "In future work, we will conduct laboratory work to elucidate whether AK1 acts as a tumor promoter of AML and its underlying mechanisms." (PMID 32519744, 2020). "AK family isozymes AK1-9 have been identified in human tissues, and existing studies have reported that AK1, 2, 4, 6 and 7 subtypes function in the regulation of tumor growth, metabolism, energy allocation and invasion." (PMID 35964092, 2022). "In mouse embryonic fibroblasts, it was demonstrated that during their transformation into tumor cells, a significant reduction of AK1 expression occurs." (PMID 32509571, 2020). "To test if this phenomenon may be relevant in clinical practice, we analyzed a cohort of 79 Cytarabine-treated AML patients for AK1 expression using immunohistochemistry (tumor samples were taken at diagnosis before therapy)." (PMID 32686665, 2020). "In this context, experiments on mouse embryonic fibroblast have shown that during their transformation into tumor cells, augmentation of AK1 might be related to the downregulation of AK1β." (PMID 32509571, 2020). "Based on this, we separated the interface cluster into two subclusters, and confirmed that the two subclusters express anti-correlated levels of tumor markers such as BRAFV600E, mitfa, and pmela, and muscle markers such as ckba, neb, and ak1." (PMID 34725363, 2021). "Notably, radiation induced upregulation of AK1 and DCXR, regulatory factors known to enhance glycolysis in microglia and tumor cells, an effect that was mitigated following microglia replenishment." (PMID 40390112, 2025).
cancer (8 papers, 2010 to 2025). A tumor composed of atypical neoplastic, often pleomorphic cells that invade other tissues. "Studies indicate that AK isoforms (AK1, AK2, AK4, and AK6) have an important role in the regulation of cancer cell metabolism, metabolic signaling, and cell migration and invasion." (PMID 32509571, 2020). "Specifically, we will overview how AK isoforms, localized in mitochondria (AK2 and AK4), and their main communication partners cytosolic AK (AK1 and AK6) are involved in cancer formation and metastasis." (PMID 32509571, 2020).
neurodegenerative disease (3 papers, 2023 to 2025). A disorder of the central nervous system characterized by gradual and progressive loss of neural tissue and neurologic function. "AK1 is also highly expressed in the brain and plays important roles in degenerative diseases involving inflammation, hypoxic conditions and oxidative stress." (PMID 38166692, 2024). "Regarding the neuroscience field, where SIRT2 inhibition seems to be an efficient pharmacologic strategy, AK-1, AK-7, and AGK-2 are the most used inhibitors in cellular and in vivo models of neurodegenerative diseases." (PMID 38132302, 2023). "In this sense, even though AK-1 (IC50 = 12.5 μM) is more potent than AK-7 (IC50 = 15.5 μM), it lacks blood–brain barrier (BBB) permeability, a crucial characteristic for the treatment of neurodegenerative diseases." (PMID 38132302, 2023).
AK1 also shares sentences with these, for which no sentence is quoted: African trypanosomiasis (1 paper); brain tumors (1); Cerebral ischemia (1); dementia (1); heart failure (1); hemoglobinopathies (1); hypertrophic cardiomyopathy (1); invasive ductal carcinoma (1); leukemia (1); malaria (1); male infertility (1); nonspherocytic hemolytic anemia (1); oligoasthenoteratozoospermia (1); Parkinson (1); Pituitary adenoma (1); prostate (1); prostate carcinoma (1); thyroid cancer (1).